ICAM3 (intercellular adhesion molecule 3)
Description:
Cell adhesion molecule that functions as a receptor ligand of the signaling receptor ITGAL:ITGB2/LFA-1 (lymphocyte-function associated (LFA) molecule 1) ensuring apoptotic neutrophil phagocytosis by macrophages. Is also a ligand for integrin ITGAD/ITGB2. Ligand of CD209 on dendritic cells (DC) through an integrin-independent mechanism that requires Ca(2+) and that forms a first contact between DC and resting T cell, facilitating the downstream DC-T cell clustering process and DC-induced proliferation of resting T Cells.
Synonyms: CD50; CDW50; ICAM-R
Tractability: Antibody: a drug acting on it is in phase 2 or 3 trials; its Gene Ontology location is reachable by antibodies, with high confidence; UniProt predicts a signal peptide or a membrane-spanning region. PROTAC: ubiquitination databases record sites on it; its protein half-life has been measured.
Target class: Adhesion
Gene: Protein-coding gene on chromosome 19 (10,333,776 to 10,339,847, reverse strand). Ensembl gene ENSG00000076662.
Subcellular location: Cell membrane
Subcellular location (Human Protein Atlas): Mitochondria; Nuclear membrane; Nucleoplasm
Pathways (Reactome):
Immune System: CD209 (DC-SIGN) signaling; Immunoregulatory interactions between a Lymphoid and a non-Lymphoid cell
Extracellular matrix organization: Integrin cell surface interactions
Gene Ontology:
Molecular function: integrin binding; protein binding; receptor ligand activity; signaling receptor binding
Biological process: cell-cell adhesion mediated by integrin; immature T cell proliferation; immune response; integrin-mediated signaling pathway; leukocyte cell-cell adhesion; cell adhesion; cell-cell adhesion
Cellular component: extracellular exosome; plasma membrane; membrane
Genetic constraint (gnomAD): Loss-of-function variants: 54 observed, 44.04 expected, observed/expected ratio (o/e) 1.23, 90% interval 0.98 to 1.54. The upper end of that interval is the gene's LOEUF score, 1.54, which puts it in group 6 of 6, group 1 being the genes least tolerant of losing a copy. Missense variants: 715 observed, 738.79 expected, observed/expected ratio (o/e) 0.97, 90% interval 0.91 to 1.03. Synonymous variants: 306 observed, 323.04 expected, observed/expected ratio (o/e) 0.95, 90% interval 0.86 to 1.04.
Homologues: Orthologues: chimpanzee ICAM3 (98% identical), dog ICAM3 (63% identical), rabbit ICAM3 (61% identical), pig ICAM3 (40% identical), zebrafish si:ch211-66e2.3 (12% identical), zebrafish icam3 (12% identical), zebrafish si:ch211-66e2.5 (11% identical), zebrafish sc:d0202 (11% identical), zebrafish si:ch73-208g10.1 (11% identical), zebrafish si:ch211-74m13.1 (8% identical). Paralogues in human: ICAM5 (50% identical), ICAM1 (46% identical), ICAM2 (15% identical), ICAM4 (13% identical).
Diseases named in the same sentence as ICAM3 in open-access papers:
ICAM3 is named in the same sentence as 73 diseases in open-access papers, as found by Europe PMC text mining. Sharing a sentence is not in itself a finding about the gene and the disease. The quoted sentences say what the papers report.
COVID-19 (4 papers, 2021 to 2022). A disease caused by infection with severe acute respiratory syndrome coronavirus 2. "Asymptomatic COVID-19 cases displayed upregulation of ISGs and humoral response genes with downregulation of ICAM3 and TLR8." (PMID 34824360, 2021).
diabetes (4 papers, 2019 to 2026). "Individuals with diabetes at baseline had higher levels of E-Selectin, P-Selectin and ICAM3." (PMID 30816120, 2019). "Taken together, our results suggest that biomarkers of vascular injury and platelet activation (E-Selectin, P-Selectin, TPO, TM, ICAM3, and GPIIb/IIIa) are associated with established CVD risk factors, particularly sex, alcohol consumption, diabetes, and exogenous hormone use." (PMID 30816120, 2019).
HIV-1 infection (4 papers, 2017 to 2024). The type species of lentivirus and the etiologic agent of acquired immunodeficiency syndrome (AIDS). "DC-SIGNR, as it has a high affinity for ICAM-3, can capture the mannose glycans present on HIV-1 gp120 and promote HIV-1 infection of T cells in trans." (PMID 28109307, 2017). "Exosomes purified from breast milk can inhibit HIV-1 infection in dendritic cells (DC) by binding to dendritic cell specific intercellular adhesion molecule 3 (ICAM-3) grabbing non-integrin (DC-SIGN) resulting in blocking viral transfer." (PMID 28961190, 2017).
lung carcinoma (4 papers, 2020 to 2025). "The same group has investigated the migration process of the MMP enzyme, and also examined the effect of ICAM3 on apoptosis in lung cancer cell line H1299, discovering that ICAM3 was able to inhibit the apoptotic process of H1299 cells, possibly through the activation of the AKT-CREB pathway." (PMID 39991572, 2025).
myeloma (4 papers, 2022 to 2025). "The analysis showed that BCMA, ICAM3 (CD50), CD221, and CS1 (SLAMF7) are the most abundantly expressed markers at all stages of myeloma, with BCMA, ICAM3, and CD221 being expressed at significantly higher levels in diseased rather than precursor PCs." (PMID 39991572, 2025). "Our analysis showed BCMA, ICAM3 (CD50), CD221, and CS1 (SLAMF7) as the most abundantly expressed markers on PCs across all myeloma stages, with BCMA, ICAM3, and CD221 having significantly higher expression levels on disease versus precursor PCs." (PMID 37723227, 2023). "GGT1, ICAM3/CD50, and ICAM1/CD54, earlier identified in the myeloma cell line proteomics, were among the most enriched proteins on the primary myeloma cell surface relative to B-cells." (PMID 35840578, 2022).
autoimmune disease (3 papers, 2017 to 2025). A disorder resulting from loss of function or tissue destruction of an organ or multiple organs, arising from humoral or cellular immune responses of the individual to their own tissue constituents. "While implicated variants were largely trait-specific, 40% of target genes of these variants (2,207 of 5,488) were implicated across more than one autoimmune disorder, with 11 genes implicated across a maximum of 9 traits (e.g., TYK2, ICAM1, ICAM3, TNFIP3, CLEC16A, BACH2)." (PMID 41361473, 2025). "ICAM-3, a member of the ICAM immunoglobulin family of adhesion molecules, binds to leukocyte function antigen and mediates the initial localization of neutrophils to sites of tissue injury and inflammation in autoimmune diseases." (PMID 29228005, 2017).
breast carcinoma (3 papers, 2020 to 2025). "Moreover, ICAM3, CCL16, PDE3A, PRTN3, TRAF6, BCAR1, IL-1α, IL-1β, NFκB1, SOX2 and OCT4 decreases the protein expression as indicated by immunofluorescence staining in the ibuprofen-treated MDA-MB-231 breast cancer cells versus the control." (PMID 32528119, 2020).
cervical cancer (3 papers, 2008 to 2025). A primary or metastatic malignant neoplasm involving the cervix. "Further data analysis of the case samples concluded that ICAM3 was associated with radiotherapy resistance in cervical cancer." (PMID 39991572, 2025). "A study indicated ICAM-3 overexpression is associated with radiation resistance in cervical cancer cells." (PMID 31426855, 2019). "Intercellular adhesion molecule 3 expression was reported to associate with radioresistance in cervical cancer." (PMID 18349842, 2008). "It was concluded that the expression of ICAM3 could be a valuable biomarker to predict the radiation resistance of cervical cancer during radiotherapy." (PMID 39991572, 2025).
endothelial dysfunction (3 papers, 2018 to 2026). In vascular diseases, endothelial dysfunction is a systemic pathological state of the endothelium (the inner lining of blood vessels) and can be broadly defined as an imbalance between vasodilating and vasoconstricting substances produced by (or acting on) the endothelium. "ICAM3 significantly increased under hypoglycemia and at 24 h post hypoglycemia in the combined cohort, but compared to controls, T2D subjects had decreased levels at 2 and 24 h post hypoglycemia, suggesting endothelial dysfunction that differs between those with T2D and those without T2D." (PMID 41596469, 2026). "Overall, cadherin-5 and sTie-2, together with increases in P-selectin, ICAM3, ANGPT1 and PAI-1, suggest that hypoglycemia may result in a shift from endothelial stability to an inflammatory, pro-adhesive and pro-thrombotic phenotype, indicating worsening endothelial dysfunction after baseline." (PMID 41596469, 2026).
ischemic stroke (3 papers, 2024 to 2025). A stroke disorder caused by obstruction of blood flow to the brain, due to thrombotic (local blood clot formation) or embolic (due to a blood clot or other material traveling from another site) event. "Supporting this hypothesis, elevated circulating levels of intercellular adhesion molecule 3 (ICAM-3), a biomarker of endothelial activation and leukocyte-endothelial interaction, have been prospectively associated with increased ischemic stroke risk in population-based cohorts." (PMID 41497398, 2025). "While there are studies suggesting that increased circulating ICAM3 is associated with the risk of acute ischemic stroke, the relationship between serum levels of ICAM3 and the severity and short-term prognosis of ischemic stroke is not clear." (PMID 39991572, 2025).
melanoma (3 papers, 2012 to 2022). A malignant, usually aggressive tumor composed of atypical, neoplastic melanocytes. "Poly (lactic-co-glycolic acid) (PLGA) nanoparticles containing tètanus toxoid and gp100 melanoma-associated antigen, toll-like receptor adjuvants were targeted to the DC-SIGN receptor in DCs by specific humanized antibodies or by ICAM3-Fc fusion proteins, which acts as the natural ligand." (PMID 31083610, 2019). "Here, we showed that EVs from the metastatic melanoma cells inhibit the release by keratinocytes of the IL6, IL8, IL10, and IL12 immunomodulatory cytokines and the regulators of cell adhesion and immune cell infiltration, such as sICAM-1, s-ICAM-3, sPECAM-1, sE- and sP-selectins, t-PA, and sCD40L." (PMID 35327461, 2022). "ICAM-3 is expressed by THP-1 myeloid cells and Jurkat lymphoid cells but not by erythroleukemic or melanoma cell lines like K-562 or BLM cells." (PMID 22479382, 2012).
psoriasis (3 papers, 2019 to 2025). An autoimmune condition characterized by red, well-delineated plaques with silvery scales that are usually on the extensor surfaces and scalp. "Meanwhile, LTA, TDRKH, and DDR1 were expressed exclusively in T cells from psoriasis biopsy samples, while HLA-E and ICAM3 exhibited psoriasis-specific- expression." (PMID 40564099, 2025).
Cirrhosis (2 papers, 2025). A chronic disorder of the liver in which liver tissue becomes scarred and is partially replaced by regenerative nodules and fibrotic tissue resulting in loss of liver function. "We demonstrated that HPS in PSVD is characterized by high plasma concentration of angiogenic mediators (Angiopoietin 2, ICAM3, and Tie2), similarly to what happens in cirrhosis." (PMID 40171298, 2025). "In this regard, increased plasma concentrations of several angiogenic mediators, including angiopoietin 2, TEK tyrosine kinase endothelial (Tie2), intercellular adhesion molecule 3 (ICAM3), and vascular cell adhesion molecule 1 (VCAM1), are increased in patients with HPS and cirrhosis." (PMID 40171298, 2025). "In both PSVD and cirrhosis, patients with HPS had higher plasma concentrations of ICAM3 and Angiopoietin 2 than those without HPS." (PMID 40171298, 2025).
epilepsy (2 papers, 2023 to 2025). A brain disorder characterized by episodes of abnormally increased neuronal discharge resulting in transient episodes of sensory or motor neurological dysfunction, or psychic dysfunction. "We identified five significant genes (WIPF1, IQSEC1, JAM2, ICAM3, and ZNF143) that had causal relationships with epilepsy." (PMID 37246165, 2023). "Therefore, we speculate that ICAM3 may have a potential role in inflammation-related epilepsy, though further research is needed." (PMID 37246165, 2023).
Stroke (2 papers, 2024 to 2025). Sudden impairment of blood flow to a part of the brain due to occlusion or rupture of an artery to the brain. "In addition, regression analysis revealed that elevated serum ICAM3 levels were associated with a poorer short-term functional prognosis for stroke." (PMID 39991572, 2025). "The patients were followed for 2 weeks after admission to the hospital for functional prognosis, and serum ICAM3 concentrations were found to be independent of stroke severity at baseline according to the National Institutes of Health Stroke Scale and infarct volume." (PMID 39991572, 2025).
type 2 diabetes (2 papers, 2019 to 2025). "No studies on ICAM3, thrombopoietin, and GP IIb/IIIa in relation to type 2 diabetes risk were found." (PMID 31783601, 2019).
viral infection (2 papers, 2021 to 2023). "Due to DC-SIGN’s role in the process of viral infection and its structural complexity, many groups believe that blocking the sugar binding site, ICAM-3 epitope in the carbohydrate recognition domain (CRD) will overall inhibit DC-SIGN and not allow the virus to enter." (PMID 34452377, 2021).
Arenavirus infection (1 paper, 2024). "Overexpression of C-type lectin receptor dendritic cell specific intercellular adhesion molecule-3-(ICAM-3) grabbing non integrin (DC-SIGN) or the liver/lymph node specific ICAM-3-grabbing non-integrin (L-SIGN) lead to an enhancement of NW Arenavirus infection, specifically for JUNV." (PMID 38908736, 2024).
Crohn disease (1 paper, 2024). A gastrointestinal disorder characterized by chronic inflammation involving all layers of the intestinal wall, noncaseating granulomas affecting the intestinal wall and regional lymph nodes, and transmural fibrosis. "ICAM-1 levels are increased in colon tissue from ulcerative colitis and Crohn’s disease, whereas ICAM-3 is elevated only in Crohn’s disease; in contrast, ICAM-2 levels are unaltered in both diseases." (PMID 38391953, 2024).
gestational diabetes (1 paper, 2026). Carbohydrate intolerance first diagnosed during pregnancy. "In humans, newborns of overweight women with gestational diabetes were more likely to display a systemic inflammation manifested by increased levels of IL‐6, IL‐8, ICAM3, TNFR1 and VEGFR2, creating a milieu that predisposes to obesity." (PMID 41085141, 2026).
Hodgkins lymphoma (1 paper, 2014). A heterogeneous group of malignant lymphoid neoplasms of B-cell origin characterized histologically by the presence of Hodgkin and Reed-Sternberg (HRS) cells in the vast majority of cases. "ICAM-3 (CD50) is constitutively expressed on most B-cell malignancies, except for Hodgkin lymphoma, and myeloid cells, but appears to be absent from other tissues, with the possible exception of tumor-associated vasculature." (PMID 24959420, 2014).
Hypoglycemia (1 paper, 2026). A decreased concentration of glucose in the blood. "Post hypoglycemia, E-selectin, P-selectin and ICAM3 were significantly lower in T2D patients at 2 h, while PAI-1 was significantly lower at 4 h and ICAM3 was significantly lower at 24 h." (PMID 41596469, 2026). "Post hypoglycemia, P-selectin was significantly increased at 30 min (p = 0.01), 1 h (p = 0.01) and 24 h (p = 0.03), and ICAM3 was significantly increased at 24 (p = 0.047) in both T2D and controls compared to baseline (respectively)." (PMID 41596469, 2026). "Under hypoglycemia, decreases in cadherin-5 and soluble angiopoietin-1 receptor (sTie-2) were observed, with increased P-selectin, intercellular adhesion molecule-3 (ICAM3), ANGPT1 and PAI-1." (PMID 41596469, 2026). "In addition, there were increases in both P-selectin and ICAM3 that were maintained at 24 h, suggesting platelet–endothelial activation in accordance with potentially persistent pro-inflammatory and pro-thrombotic vascular changes after hypoglycemia." (PMID 41596469, 2026). "Post hypoglycemia, decreased cadherin-5 and ICAM5 were observed at 2 h and PAI-1 at 4 h, as well as increases in P-selectin at 30 min, 1 h and 24 h and ICAM3 at 24 h." (PMID 41596469, 2026). "In the combined cohort, upon induction of hypoglycemia, there were significant decreases in cadherin-5 (p = 0.01) and sTie-2 (p = 0.01) and significant increases in P-selectin (p < 0.01), PAI-1 (p < 0.001), ANGPT1 (p < 0.001) and ICAM3 (p = 0.03) compared to baseline." (PMID 41596469, 2026).
malaria (1 paper, 2023). Malaria is a serious and sometimes fatal disease caused by a parasite that commonly infects a certain type of mosquito which feeds on humans. "The involvement of Integrins αV and PECAM-1 in CM has been reported; however, the significance of ICAM-3 and N-cadherin in malaria disease has not been established yet." (PMID 37048057, 2023).
metastatic melanoma (1 paper, 2022). A melanoma that has spread from its primary site to another anatomic site. "In line with this, the bioinformatic analysis of the TCGA database revealed that the high expression of the genes coding IL6, IL10, IL12, ICAM-1, ICAM-3, PECAM-1, and CD40L in tissues of patients with metastatic melanoma correlates with the better survival prognosis." (PMID 35327461, 2022).
myocardial infarction (1 paper, 2019). Gross necrosis of the myocardium, as a result of interruption of the blood supply to the area, as in coronary thrombosis. "Thus, we evaluated associations between six novel markers (E-Selectin, P-Selectin, thrombomodulin, thrombopoietin, intercellular adhesion molecule 3 and GPIIb/IIIa) and established cardiovascular risk factors as well as the risk of myocardial infarction (MI) in a population-based study." (PMID 30816120, 2019).
pancreatic cancer (1 paper, 2020). "The methylation status of GRAP2, ICAM3, A2ML1, MUC1, and MUC4 can influence the expression of these genes, which is associated with survival of pancreatic cancer." (PMID 33302876, 2020).
pterygium (1 paper, 2025). A wedge-shaped fibrovascular lesion arising from the bulbar conjunctiva and extending to the cornea. "ICAM2 and ICAM3 protein expressions were also significantly increased in pterygium tissues (p = 0.0116 and p = 0.0252, respectively)." (PMID 39991572, 2025). "The results showed a significant increase in ICAM2 and ICAM3 gene expression in pterygium tissues (p = 0.0018 and p = 0.0023, respectively)." (PMID 39991572, 2025). "There was a significant positive correlation between pterygium grade, ICAM2 protein expression (p = 0.0398), and ICAM3 immunohistochemical score (p = 0.0138)." (PMID 39991572, 2025).
triple-negative breast carcinoma (1 paper, 2024). An invasive breast carcinoma which is negative for expression of estrogen receptor (ER), progesterone receptor (PR), and human epidermal growth factor receptor 2 (HER2). "Notably, the TRs of several genes, including SYNGR1, GTF2IRD2, and FAM120C, exhibited increased levels in the tumor samples of triple-negative breast cancer patients, whereas genes such as TVP23C, ICAM3, and RIMKLB displayed decreased TRs in triple-negative breast cancer tumor samples." (PMID 39349823, 2024).
vasculitis (1 paper, 2023). "ITGB2 (CD18) a receptor for ICAM1, ICAM2, ICAM3, and ICAM4, is a potential mechanistic biomarker for vasculitis." (PMID 38274452, 2023).